IFNG (interferon gamma)
Diseases named in the same sentence as IFNG in open-access papers (continued):
Sharing a sentence is not in itself a finding about the gene and the disease.
tumor (continued). "Simultaneously, they suppress the secretion of pro-inflammatory cytokines such as interferon-gamma (IFN-γ), weakening the immune response and further promoting tumor progression." (PMID 40585979, 2025). "CD8+ T cells can secrete granzyme B (GZMB) and interferon-gamma (IFN-γ), enhancing their cytotoxicity against tumor cells." (PMID 40346484, 2025). "This can be explained by a requirement for CD4+ T helper cells to convert them to IFNγ-producing cells resulting in effective tumor therapy and reduction of Tregs." (PMID 40813233, 2025). "The proliferation of IFNγRKO tumour cells, as assessed by KI67 staining, was greater than the one of WT tumour cells, demonstrating that IFNγ inhibits tumour cell proliferation, which contributed to the selection of IFNγRKO over WT tumour cells." (PMID 39746898, 2025). "Oncogenic signalling pathways such as PI3K/AKT, MAPK, and MYC affect constitutive PD-L1 expression, while pro-inflammatory cytokines, particularly interferon-gamma (IFN-γ) produced by tumour-infiltrating lymphocytes (TILs), induce adaptive PD-L1 expression." (PMID 41284319, 2025). "IFNγ stimulates Fas expression on the tumor cells, rendering them more sensitive to contact‐dependent killing by T‐cells or other cells expressing Fas ligand (FasL)." (PMID 40178291, 2025). "We analyzed IFNG transcriptome sequencing data from the TCGA cohort and found that IFNG levels were significantly higher in tumor tissue compared to normal tissue (****P < 0.0001)." (PMID 41368643, 2025). "CIML-NK cells are preconditioned with cytokines to acquire enhanced memory-like functions, can quickly produce high levels of IFNγ and cytotoxic responses when encountering tumor cells." (PMID 40094019, 2025). "M1 macrophages are activated by inflammatory cytokines, such as interferon gamma (IFN-γ) and tumor necrosis factor alpha, and produce proinflammatory cytokines for eliminating pathogens, tumor cells, and damaged tissues." (PMID 41162494, 2025). "This places ACSL5 as a potential candidate biomarker and a promising therapeutic target, situated at the nexus of IFNγ signaling, anti-tumor immunity and alloimmunity." (PMID 40546938, 2025). "Estrogen suppresses CD8+ T-cell activity by reducing the production of interferon-gamma, thereby dampening their anti-tumor functions." (PMID 39926277, 2025). "Results from studies in experimental models of malignancy further suggest that intratumoral administration of IL-33 can promote effector T cells infiltration, increase interferon-gamma (IFN-γ) production, and slower tumour growth." (PMID 41284319, 2025). "For Triple‐I tumors, in addition to IFNG mediated cytotoxic T‐cell tumor killing involving genes, like GZMB, high AIM2 along with NLRP1 expression support a role of pyroptosis via inflammasomes." (PMID 40492347, 2025). "Our work thus serves mechanistic insight for the crosstalk between tumour IFNγ resistance and anti-tumour immunity, and implicates this regulation for future cancer therapy." (PMID 39746898, 2025). "In contrast to short-term IFNγ stimuli, chronic IFNγ stimulation activated the expression of immune inhibitory factors, leading to T cell exhaustion and tumor immune evasion." (PMID 39667501, 2025). "In melanoma, mutations in the IFNγ-JAK-STAT pathway drive resistance to checkpoint inhibitors but, paradoxically, increase tumor sensitivity to oncolytic VSV treatment." (PMID 41294689, 2025). "IFNG is a cytokine critical for innate and adaptive immunity against viral and intracellular bacterial infections and for tumor control." (PMID 40919176, 2025). "They observed that L1CAM-specific CAR-T cells infiltrated the 3D tumor model from the top to the bottom, displaying strong activation marked by increased interferon-gamma (IFNG) release and potent tumor-killing capacity." (PMID 41488666, 2025). "Previous investigations have shown that tumor cells are more transcriptionally active and there is increased localized production of IFNγ at the tumor immune boundary." (PMID 41446806, 2025).
tumor (continued). "In contrast, CD25 and IFNγ expression levels remained negligible in the presence of NY-ESO1-negative tumor target cells for most of these tested DARPin TCEs." (PMID 41321628, 2025). "This dynamic suggests a feedback mechanism in which IFNG derived from NK cells activates monocytes, contributing to an inflammatory tumour microenvironment." (PMID 41357186, 2025). "Nano-IFNγ/Zole, which was dispersed in gel, was injected into the peripherally ablated tumor during the final stage of surgery." (PMID 39776793, 2025). "There is a similar link between PD-1+ T cells infiltrating tumors which leads to upregulation of tumor PD-L1 through the release of IFNγ." (PMID 41415295, 2025). "This immunostimulatory effect was also observed systemically, as evidenced by the increase in tumor-specific IFNg-producing cells in the spleens of IL-P60750 mice treated." (PMID 39075226, 2025). "In one study, breast cancer cells metastasising to the liver were found to increase the number of NK cells in the liver, upregulate IFNγ expression, and maintain tumour cells in a dormant state with smaller cell volumes." (PMID 40525649, 2025). "In the TME, T cells release interferon-gamma (IFN-γ) to kill tumor cells after recognizing abnormal antigens through the MHC I pathway." (PMID 40012016, 2025). "Tumor cells treated with ferroptosis inducers showed increased sensitivity to Interferon gamma (IFN-γ) secreted by ROR1 CAR-T cells." (PMID 39849645, 2025). "Meanwhile, co‐culture assay showed c‐MYC knockdown EG7 cells exhibited enhanced IFNγ secretion level of OT‐I cells as compared with that of control tumor cells, and I3A treatment further increased T cell activation levels." (PMID 40583248, 2025). "In contrast, iNKT in adjacent non-tumor tissue predominantly produced IFNγ, highlighting the critical impact of the local microenvironment on iNKT functional polarization." (PMID 40718496, 2025). "High tumour mutation burden (TMB) and interferon gamma (IFNγ)-related gene expression are key predictors of ICI response." (PMID 41291768, 2025). "Growth factors such as EGF, VEGF, FGF, IL‐10, IL‐6, TNF‐α, IFNγ produced by TAMs and NKs and miRNAs carried in tumour‐derived EVs promote tumour proliferation by activating pathways such as RAS–RAF–MEK–ERK–MAPK and PI3K–AKT–mTOR." (PMID 40525649, 2025). "SOX17 inhibits tumor cells’ ability to sense and respond to IFNγ, thereby preventing anti-tumor T cell responses." (PMID 39889187, 2025). "In adaptive immune response, tumor-engaged effector T cells secrete interferon-gamma (IFN-γ), which induces PD-L1/L2 expression on tumor cells." (PMID 40940864, 2025). "XUC treatment significantly enhanced IFNγ activation in co-cultures of immune cells with both target MB49 tumor cells and XUC cells, indicating a robust immune response." (PMID 40805151, 2025). "We employed single-cell RNA sequencing (scRNAseq) of the CD45+ compartment isolated from pooled tumour samples to better understand the immunological changes which enable effective control of IFNγ-insensitive tumours." (PMID 39746898, 2025). "Further functional analyses revealed highly correlation between CS polarity and immune-related (IFNγ,IFNα and cytokines) along with oncogenic signaling (hypoxia and angiogenesis), suggesting an anti-tumor or pro-tumors status globally." (PMID 40230843, 2025). "The up-regulation of Ifngr1 expression in Il1r2−/− iCAF can potentially help enhance the response to interferon-gamma and promote anti-tumor immunity." (PMID 40767963, 2025). "The proportion of M2-type macrophages decreased while more M1 macrophages were distributed in tumor tissues treated with Nano-IFNγ/Zole." (PMID 39776793, 2025). "Given that only a small fraction of administered CAR-T cells initially reach the tumor, robust IFNγ production likely plays a decisive role in their subsequent expansion and overall therapeutic efficacy." (PMID 41154636, 2025).
tumor (continued). "interferon-gamma (IFNγ) plays a critical role in the anti-tumor immune response during immunotherapy." (PMID 39788975, 2025). "Anti-TIM-3 antibodies have been shown to suppress tumor development and enhance IFNγ-mediated antitumor immunity in preclinical cancer models." (PMID 40332725, 2025). "Tumor growth curves clearly showed that the administration of Nano-IFNγ/Zole after iRFA delayed residual tumor proliferation compared to iRFA treatment alone." (PMID 39776793, 2025). "With CRT-NP, decrease in tumor infiltration of Treg cells (CD4+ FOXP3+) cell was observed as well as increase in IFNγ expression on CD4+ T cells." (PMID 40386779, 2025). "Interferon-gamma (IFN-γ) inhibits BMSC-mediated tumor growth and stimulates antigen-presenting cells to activate T lymphocytes." (PMID 40181963, 2025). "Our results demonstrated that the hallmarks of interferon alpha response and interferon gamma response, which are both indicative of the potency of antiviral and anti-tumor immune responses, were all enriched in the RRShigh group (adjusted p < 0.001)." (PMID 41001426, 2025). "The concurrent decrease in IFNγ and IL-8 further supports a defective Th1-mediated effector function and impaired inflammatory signaling, indicating a shift from protective anti-tumor immunity toward chronic, dysregulated inflammation." (PMID 41425582, 2025). "On the contrary, it was negatively correlated with cytokine‐encoding related genes such as IFNG, GZMB, PRF1, and TNF in most tumor types." (PMID 40013761, 2025). "Overall, our data demonstrate that the CD8/monocyte crosstalk occurs around vessels in IFNγ-insensitive tumours, where CD8 T cells recruit monocytes and skew their differentiation." (PMID 39746898, 2025). "In particular, production of IFNγ, a cytokine of high relevance in tumor immunology and in cytotoxicity, was strongly inhibited." (PMID 40143032, 2025). "It is an important immunomodulatory protein that enhances the production of interferon-gamma (IFN-γ) by tumor antigen-specific CD4+ T cells, which in turn strengthens the cytotoxic function of CD8+ T cells, ultimately inhibiting tumor growth." (PMID 41445755, 2025). "NeoVax, engineered by stratification of different tumor regions to counteract GBM heterogeneity, boosted IFNγ-producing T cells and augmented tumor infiltration." (PMID 40893155, 2025). "One study explored the influence of a composite model including interferon gamma (IFN-γ) and tumour PD-L1 expression in both biopsy and resection specimens." (PMID 41487587, 2025). "Altogether, the huCC49-IL-2 treatment resulted in the generation of a potent anti-tumor immune environment, as evidenced by the changes in IFNγ+CD8+ T to CD4+ T-reg ratios." (PMID 40361381, 2025). "Th17 cells are thought to suppress tumor growth, induce tumor cell apoptosis, and inhibit angiogenesis by releasing cytokines like IFNG and TNFA in HCC." (PMID 40436857, 2025). "When IVIS imaging of tumors was performed after 2 weeks, a favorable amount of Cy5-labeled IFNγ was detected in the tumor tissue." (PMID 39776793, 2025). "Both, ILs and free P60 (at a dose 50 times higher than encapsulated) were able to increase statistically IFNγ levels and Granzyme B expression in tumor CD8+ T cells." (PMID 39075226, 2025). "PD-L1 expression in tumor cells is positively regulated by interferon gamma (IFN-γ) secreted by activated T cells and other antigen-presenting cells." (PMID 40508074, 2025). "In vivo IFNγ stimulation can substantially elevate tumor PD-L1 expression, confounding the assessment of therapeutic efficacy and selection of antibody drugs based on PD-L1 and other tumor factors used as immune checkpoint inhibitors in clinical settings." (PMID 40001596, 2025). "In an independent study, qPCR and ELISA revealed higher IFNγ abundance in MC38 tumor lysates and serum of DKO mice compared to DWT mice, respectively." (PMID 40475851, 2025).
tumor (continued). "By correlating IFNG expression with histopathological features, we were able to develop a model that not only predicts IFNG status but also provides insights into the tumor microenvironment." (PMID 41368643, 2025). "We found abundant presence of CD4+ T cells in the tumor microenvironment, which have been reported to produce cytotoxic interferon gamma and induce senescence of tumor cells." (PMID 40613043, 2025). "T cell-predominant models require different approaches, as T cell-engaging tumor organoid platforms showed enhanced CD8+ T cell activation with increased interferon-gamma (IFN-γ) and granzyme B (GZMB) expression when treated with epigenetic inhibitors." (PMID 41155895, 2025). "Mechanistically, IFNγ receptor deletion in B16-F10 tumours increases IFNγ availability, triggering a remodelling of the immune landscape characterised by inflammatory monocyte infiltration and the generation of ‘mono-macs’." (PMID 39746898, 2025). "In parallel, tumour-secreted IFNG significantly inhibited M2-like macrophage polarization with comparable effects between AAVS1 and RPLP0 targeting, but a tendency toward dose dependency when comparing pre-sort to post-enrichment conditions." (PMID 41366257, 2025). "M1-polarized TAMs, particularly in HGSOC, secrete CXCL10 in response to IFNγ signaling, which attracts T-cells into the tumor microenvironment." (PMID 40330466, 2025). "Preclinical studies first demonstrated that bEVs can selectively accumulate in tumor tissues and trigger potent antitumor immune responses via interferon-gamma (IFN-γ) signaling in murine models." (PMID 41463196, 2025). "Following stimulation, the percentage of CD8+ T cells expressing IFNγ or CD44 was similar in young and old mice, suggesting that tumor-associated T cells from both age groups can be activated at similar levels." (PMID 41332581, 2025). "Activated T cells release IFNγ in the tumor, upregulating PD-L1 expression on tumor and immune cells, thereby driving rebound immunosuppression and adaptive resistance." (PMID 39941761, 2025). "Immune cells isolated from tumors 7 days after virotherapy were stimulated with an Adpgk-R304M peptide to analyze tumor-specific CD8+ T-cell responses by intracellular IFNγ staining." (PMID 39789356, 2025). "The combination of all three inhibitors resulted in a tumor microenvironment characterized by increased IFNγ-producing CD4+ T cells, decreased CD4+FOXP3+ T regulatory cells (Tregs), and decreased IL-10-producing CD4+ T cells." (PMID 40904502, 2025). "The tdLN of tumor-bearing mice features increased numbers of IFNγ-producing CD8+ T cells compared to naïve mice, yet these numbers do not further increase after treatment." (PMID 40230629, 2025). "This combination altered the TME, increased the infiltration of cytotoxic CD8+ T cells into the tumor site, and elevated interferon gamma (IFNγ) levels." (PMID 40977714, 2025). "Resting CD94+CD16+ NK cells have limited interferon gamma but upon activation by tumor cells produce high levels of interferon gamma." (PMID 41445756, 2025). "Activation of IFNγ signaling is central to immune responses leading to tumor clearance and approaches that kick-start this pathway have shown promise in overcoming ICI resistance." (PMID 40560386, 2025). "Neutralizing CXCL2 in the culture supernatant of DTX2‐overexpressing tumor cells and neutrophils partially restored IFNγ expression and proliferation of CD8+ T cells, while neutralizing CXCL6 did not." (PMID 39733452, 2025). "Again, mice treated with Ad-E7 in combination with immune checkpoint inhibitors showed marked increases in both CD8 T-cells and interferon gamma levels within the tumor in comparison with the control groups." (PMID 40006746, 2025). "Our findings revealed that the PR-enriched genes were associated with tumor specific T cells, and PR patients displayed higher abundance of tumor specific T cells, evidenced by elevated levels of CD8A, CXCL13, and IFNG genes." (PMID 41422078, 2025).
tumor (continued). "Interleukin 12 (IL-12) is a highly potent pro-inflammatory cytokine that can stimulate tumor immune cells and reverse immunosuppression by inducing interferon gamma (IFN-γ) expression." (PMID 40524086, 2025). "The costimulatory effect of anti-FAP-4-1BBL on fibroblasts was evident, enhancing both IFNγ release and tumor cell killing efficiency." (PMID 40136707, 2025). "This correlated with prolonged intratumoral IFNγ release and CD86 upregulation on tumor-associated myeloid cells." (PMID 39889712, 2025). "This leads to the secretion of perforin and granzyme, interferon gamma (IFN-γ) and other inflammatory cytokines to induce apoptosis of tumor cells." (PMID 40895524, 2025). "DCP‐IL‐12/Flt3L induced interferon‐gamma (IFN‐γ)‐dependent anti‐tumor immune response and significantly upregulated intratumoral cDC1, M1‐type macrophage, and effector T‐cell ratios." (PMID 40395752, 2025). "To directly compare general safe-harbour with tumour-specific knock-in, we performed co-culture experiments using IFNG-expressing SK-N-AS cells with integrations at AAVS1 or the tumour-specific RPLP0 locus." (PMID 41366257, 2025). "Transcriptomic analysis of the residual tumor tissues showed that Nano-IFNγ/Zole significantly induced changes in the overall gene expression in tumor tissue after iRFA treatment." (PMID 39776793, 2025). "Putative tumor-specific CD8+ T cells in the TA33.Combo group displayed enhanced expression of genes associated with IFNα and IFNγ signaling, proliferation, and immune activation in both liver and LM compared to the TA33 group." (PMID 40216735, 2025). "Research has shown that adaptive immunity components CD4+ T cells, CD8+ T cells, IL12, and IFNγ are in charge of keeping tumor cells in balance by exerting immune selection pressure." (PMID 41019045, 2025). "Since murine HCC cells barely express GSDME, we ectopically expressed mGSDME and found that it enhanced the infiltration of CD8+ T cells and the production of IFNγ in the tumor microenvironment, resulting in increased tumoral sensitivity to sorafenib." (PMID 40645933, 2025). "The PD1 + killer T cells, in the presence of Interferon gamma (IFNγ), sense the tumor cells via the helper T cells and kill the PDL1- tumor cells." (PMID 40460357, 2025). "IRFA treatment and its combination with Nano-IFNγ/Zole significantly changed the distribution and proportion of various immune cell subgroups in tumor tissues." (PMID 39776793, 2025). "This property allows butyrate to exert anti-tumor effects by promoting apoptosis in cancer cells and enhancing the production of interferon-gamma (IFNγ) by effector T cells, which plays a role in anti-tumor immunity." (PMID 39946032, 2025). "We found that the combination treatment group had increased tumor-reactive IFNγ+ CD8+ T cells compared to other treatment groups." (PMID 41339438, 2025). "Currently, researchers are exploring biomarkers such as the tumor mutational burden (TMB), interferon-gamma (IFN-γ) signatures, and tumor-infiltrating lymphocytes (TILs) in order to enhance the immunotherapy’s precision." (PMID 41410866, 2025). "Th1 cells are particularly important in anti-tumor immunity as they produce cytokines like interferon-gamma (IFN-γ) that enhance the activity of cytotoxic CD8+ T cells, the primary killers of cancer cells." (PMID 40432108, 2025). "Engaged CD8 T cells release a barrage of cytokines during their attack on target tumor cells, including interferon-gamma (IFNg), tumor necrosis factor (TNF), and TNF-related apoptosis-inducing ligand (TRAIL)." (PMID 41315176, 2025). "Multicolor flow cytometry analysis revealed a significant intra-tumoral infiltration of CD8+ and IFNγ+CD8+ T cells in the tumor tissues of the CTSE knockdown group and anti-PD-1 combination treatment group." (PMID 40467555, 2025).